TNF (tumor necrosis factor)
Diseases named in the same sentence as TNF in open-access papers (continued):
Sharing a sentence is not in itself a finding about the gene and the disease.
tumor (continued). "After a single high dose of ablation radiotherapy, the innate immune system is activated by inflammatory cytokines such as IL-1, TNF and M-CSF and profibrotic factors such as TGFβ, which may impair T-cell functions and promote tumor progression and recurrence by recruiting M2 macrophages." (PMID 36900416, 2023). "TNFα may promote tumours through various proposed mechanisms." (PMID 37455828, 2023). "Therefore, blocking TNFα or its receptors may have significant anti-tumor effects and inhibition of TNFα on tumorigenesis can be positive depending on the immune microenvironment and TNFα concentration." (PMID 36835413, 2023). "Although TNFα is a pleiotropic cytokine with contradictory roles in oncoimmunology, sTNFR-1-mediated inhibition of TNFα might suppress the anti-tumor activity of ICI in patients with UC." (PMID 38026978, 2023). "In particular, TNF-α, produced by tumour-associated macrophages (TAMs), modulates the overexpression of CXCL1 involved in cancer development and malignant progression; CXCL1 overexpression is associated with an aggressive form of melanoma, as it promotes tumour growth and metastasis." (PMID 37627054, 2023). "IRE1α could also regulate the expression and secretion of cytokines via XBP1 to promote tumor cell survival under ER stress, especially tumor-promoting factors like TNFα, IL-8, and VEGFα.40,41 Therefore, we wondered whether SIRT7 also regulated these cytokines with oncogenic function." (PMID 36918544, 2023). "Interestingly, UA could dose-dependently weaken the increased spleen weight in LLC tumor-bearing mice at concentrations within 200 mg/kg, and the cytokines IL-6, IL-1β, and TNF-α are produced by immune cells or tumor cells." (PMID 37190306, 2023). "In addition, the CYR61 DEGs are also linked to some tumor-suppressive pathways, including TGF-β and TNF signaling, and also to gene sets of cytokine-cytokine receptor interaction, which may play a role in remodeling the TIME." (PMID 38259466, 2023). "Moreover, they express effector molecules, which are destined to kill tumor cells, including perforin 1, granzyme B and TNFα, as well as multiple pro-inflammatory cytokines that are characteristic for activated macrophages and Th1 cells, including IL-1β, IL-6, IL-2 and IFNγ." (PMID 37174085, 2023). "Besides, KEGG analysis displayed that ICD-TDGs were related to immunity (such as chemokine signaling pathway, B/T cell receptor signaling pathway, NK-cell-mediated cytotoxicity), tumor cell death (necroptosis, TNF signaling pathway), tumor invasion (focal adhesion) and other pathways in cancer." (PMID 37388747, 2023). "During supratentorial tumor resections, systemic lidocaine administration improved early recovery quality and had neuroprotective effects, which may be attributed to its analgesic and inflammation-alleviating properties with a reduction in serum TNF-α." (PMID 36765695, 2023). "Surgical interventions or tumor-induced damage to this barrier, resulting in heightened permeability, can precipitate a systemic inflammatory response characterized by the activation of numerous inflammatory cells and the release of cytokines such as IL-1 and TNF-α." (PMID 37960219, 2023). "Similarly, thioacetamide-induced HCC rats treated with adiponectin presented an 80% increase in survival rate, a 73% reduction in average number of liver nodules, 46% decrease in serum alpha-fetoprotein (AFP), as well as a reduced expression of tumor invasion markers, TNF-α and NF-κΒ." (PMID 37958479, 2023). "Therefore, in the current study, we investigated the amount of F. nucleatum and its relationship with the expression of inflammatory genes (TLR-2, TLR-4, TNF-α, IL-6, IL-10, IL-12β, and IL-17) and miRNAs (miR-21, and miR-31) in tumor and adjacent normal tissue of Iranian CRC patients." (PMID 38075864, 2023).
tumor (continued). "Taken together, we could demonstrate that HAPLN1 expression in tumor cells modulates TNFα signaling to promote a highly plastic phenotype that facilitates invasion and colonization of the peritoneum, among others by creation of a pro-tumoral immune microenvironment." (PMID 37095087, 2023). "Besides cytotoxic events unleashed by direct interaction with tumor cells, the protective role of CD8+ T cells in the tumor microenvironment is associated with release of effector cytokines (including IFN-γ, TNF-α and IL-2) that sculpts the local immune response to cancer." (PMID 37529610, 2023). "However, TNF has also been shown to damage tumor vasculature." (PMID 38567059, 2023). "Interestingly, some of these features could be mimicked by stimulating with TNFα and inhibition of TNFα reverted the effects of HAPLN1, indicating that TNFα is responsible for the tumor cell plasticity observed in the presence of HAPLN1." (PMID 37095087, 2023). "Moreover, when antibiotic-treated tumor-bearing mice were injected with a particular bacterium (such as Alistipes shahii), the TNF production could be restored and the therapeutic outcomes could be significantly improved." (PMID 37417603, 2023). "Besides, the expression profile of TNF in tumor-infiltrating T cells was also analyzed." (PMID 36865537, 2023). "Additionally, signaling of β-hydroxybutyrate (BHB; commonly referred to as ketone) has neuroprotective effects, exhibits tumor-suppressing activity, and has an anti-inflammatory effect via downregulation of inflammatory molecules, such as TNF-α, IL-1,6,18, and prostaglandins." (PMID 36829437, 2023). "Interestingly, all data highlighted a significant positive correlation between the severity of egg infection and increased IL-1, IL-6, and TNF-α levels, indicating the possible influence of S. haematobium egg antigen on tumor-promoting cytokine levels and supporting BCa development and progression." (PMID 37068081, 2023). "Several studies demonstrated that activated basophils can secrete different cytokines involved in PCa including IL-4, which promotes tumour-promoting Th2 inflammation and M2 macrophage polarization related to a poor prognosis, IL-13, and tumour necrosis factor-alpha (TNF-α)." (PMID 38137361, 2023). "Therefore, IFN‐γ and TNF‐α secreted by CD4+ T cells play a synergistic role in the inhibition of angiogenesis in tumor tissue by cutting off the blood supply to solid tumors to reduce tumor survival and metastasis." (PMID 37829505, 2023). "In addition to the inflammatory markers and tumor markers, the pro-inflammatory cytokines, IL-1β and IL-6, and TNF-α serum detection could play an important role in diagnosis and also in prognosis, although their detection incurs increased costs." (PMID 38137862, 2023). "Besides, NK cells secrete cytokines, including IFN-γ and TNF-α, which lead to tumor growth arrest." (PMID 38008741, 2023). "However, historically, whether anti-TNFα therapies predispose people to cancer has been deeply concerned, as the relationship of tumor necrosis factor (TNF), a multifunctional cytokine, with tumor is complex." (PMID 36926334, 2023). "RA may also contribute to tumor proliferation through the secretion of IL-6, TNF- α, and IL-1β." (PMID 37876939, 2023). "Notably, TNF is known to be released by cancerous cells in the tumor microenvironment." (PMID 36874133, 2023). "Finally, b-AP15 delayed tumor growth and enhanced survival, both as a monotherapy and in combination with radiation, in HNSCC tumor xenograft models in vivo, which could be significantly attenuated by TNFα depletion." (PMID 37055579, 2023). "In fact, previous observations suggested that IFNg and TNF may suppress tumor growth in different conditions, although the ultimate effect of these cytokines on tumor progression in vivo is context-dependent as IFNg may, in fact, improve the metastasis of some tumors." (PMID 37515143, 2023).
tumor (continued). "It is found that loss of key genes in TNF signaling, IFN-γ signaling or antigen presentation pathway could enhance cancer cell resistance to CD8+ T cell-mediated killing and weaken the effect of anti-tumor immune response in vivo." (PMID 37427373, 2023). "Hence, despite their functional status ex vivo (IFN-γ and TNF production), these tumour-specific CD8+ T cells exhibited phenotypic features of exhaustion, containing populations of both transitional exhausted (PD-1+TIM-3-) and terminally exhausted (PD-1+TIM-3+) cells." (PMID 37153625, 2023). "Furthermore, tumor-associated macrophages (TAM) or myeloid-derived suppressive cells (MDSC), along with their secreted cytokines interleukin (IL)-6, tumor necrosis factor (TNF), and IL-1β, contribute to the promotion of cancer development and progression to advanced stages." (PMID 38328405, 2023). "Furthermore, G/aP@Gel + L could significantly increase the secretion of TNF-α in tumors, revealing it could enhance anti-tumor immune responses." (PMID 37165428, 2023). "In addition, they upregulate the expression of cytokines that are associated with immune response, including interferon-γ, TNF-α, IFN-g, IL-1, and IL-12, which inhibit tumour cell proliferation and induce their apoptosis, thereby exerting anti-tumour, antibacterial, and antiviral effects." (PMID 37513265, 2023). "Additionally, the role of TNF-α depends on its expression site in the tumor." (PMID 37554306, 2023). "However, morphologically-intact tumor cells along the periphery of the mechanical ablation zone appear to undergo necroptosis, a catastrophic TNFα-driven immunogenic programmed cell death pathway culminating in the formation of cell membrane pores that disrupt cellular integrity and release DAMPs." (PMID 36756111, 2023). "Therefore, TNF-α-stimulated MSCs have some anti-tumor capacity, which could provide new directions for the treatment of tumors in the future." (PMID 36814921, 2023). "Results showed that conditioned medium from FAP-over-expressed LX2 cells could decrease the expression of M1 markers like iNOS, TNF-α and IL-1β but increase the expression of M2 markers like IL-10 in macrophages as compared to NC group, transforming the macrophages into M2 pro-tumor phenotype." (PMID 37325617, 2023). "Furthermore, TNF-α expression may be different in the tumor tissue compared with the adjacent healthy liver tissue, which also should be proven, since it may bear pathophysiological and clinical implication." (PMID 37958479, 2023). "Pertinent to this, the oncogenic miR-21 has been found to be upregulated in tumours and is strongly associated with TNF-α expression and tumour progression and is a potential key mediator of metastatic potential and also, therefore, a strong candidate as a TNF-α responsive mediator." (PMID 36765584, 2023). "Additionally, these clusters also showed different enriched pathways, including cell cycle associated pathways (G2/M checkpoint, Myc targets, eIF2 targets), tumor angiogenesis pathways (angiogenesis, hypoxia), immune environment pathways (TNF-α, interferon response), and so on." (PMID 36817452, 2023). "However, TNF-α, especially its expression in tumor tissue, may be more relevant to prognosis among patients with HCC, although existing data are inconsistent." (PMID 37958479, 2023). "Chronic inflammation established by immune infiltration has been associated with tumor progression, particularly with enhanced metastasis and the EMT process through secreted factors such as transforming growth factor beta 1 (TGF-β1) and tumor necrosis alpha (TNF-α) derived from myeloid cells." (PMID 38086828, 2023). "Moreover, TNF-α was positively correlated with tumour weight in the experimental mice and considered a potent cancer cachexia factor that could be inhibited by the anti-inflammatory cytokine IL-10." (PMID 38041080, 2023). "However, tumor growth inhibition occurs only when TNF concentration is rapidly increased." (PMID 37046608, 2023).
tumor (continued). "Furthermore, tumor-derived TNF-α might lead to an additional increase in plasma IL-6 by its release from ECs." (PMID 37222464, 2023). "In addition, IBD patients have a high risk of gastrointestinal and other cancers resulting from chronic inflammation-induced tumor formation and long-term use of immunosuppressive drugs, such as azathioprine and anti-tumor necrosis factor (TNF) drugs, exerting carcinogenic action." (PMID 36830802, 2023). "Additionally, pretreatment of B16-OVA cells with AC484 led to significantly more tumour killing and cytokine production (IFNγ and TNF) by untreated SIINFEKL-specific OT-I T cells in vitro than vehicle-treated cells, a result consistent with enhanced antigen presentation." (PMID 37794185, 2023). "However, like IL-6, TNFα can also directly bind tumor cells to enhance survival and proliferation." (PMID 37461742, 2023). "On one hand, TNF has undisputed tumor-destructive function under certain circumstances; on the other hand, it is a major mediator of cancer-related inflammation and may exert tumor-promoting effects." (PMID 36926334, 2023). "During tumor progression, endothelial cells undergo an angiogenic switch, which has long been considered to be dictated by angiogenic activators, such as VEGFs, IL-8, tumor necrosis factor α (TNF-α), and hypoxia-inducible factors (HIFs) and other signaling pathways (e.g., Notch)." (PMID 37108477, 2023). "Alternatively, the expression of PD-L1 may depend on inflammatory signals, cytokines, and metabolites (i.e., IFN-α, TNF-α, IL-6) arising from the tumor cells themselves or from the TILs, the antigen-presenting cells (APC), and the tumor-associated macrophages (TAMs)." (PMID 37377735, 2023). "Furthermore, using unsupervised clustering for the de novo unbiased discovery of co-expressed gene modules, we identified a gene module characterized by TNF-α, NFκΒ and IL-17 signaling which is uniquely activated in the tumor-adjacent normal tissue of patients that eventually progress." (PMID 37938580, 2023). "Similarly, in immunomodulatory regimens and platinum-based anti-cancer therapies, bacteria-associated TLR4 agonists were shown to modulate tumor necrosis factor (TNF)- and reactive oxygen species (ROS)-mediated anti-tumor effects of tumor-infiltrating myeloid-derived suppressor cells (MDSCs)." (PMID 36828830, 2023). "However, TNF-α could stimulate proliferation, survival, migration, and angiogenesis in most cancer cells, resulting in tumor promotion." (PMID 37987366, 2023). "Therefore, the effect of LNT on p62/mTOR, NF‐κB signaling pathway, and autophagic cell death on tumor cells stimulated by TNF‐α could also depend on Nur77." (PMID 37249285, 2023). "Thus, before initiating in vivo studies, we sought to investigate the effect of CDDP on transgene expression by vectors carrying either GRP78 or CMV promoters to select the most suitable promoter to use in efficacy studies of TPA‐guided TNFα expression in tumor‐bearing mice." (PMID 37331004, 2023). "Importantly, the photothermal heat generated from AuNPs could remotely activate TNF‐α expression to kill tumor cells." (PMID 39188274, 2023). "We propose that, at the primary location, OC cells can release specific cytokines (i.e., IL-6, IL-8, IL-1β, G-CSF, GROα, MCP-1, and TNFα) to the tumor environment (i.e., peritoneal fluid) which may attract neutrophils to pro-metastatic niches (for instance, omentum) to induce NETosis." (PMID 36983067, 2023). "In addition, GPER has also been reported to inhibit inflammation, tumor cell migration, and tumor angiogenesis through reducing phosphorylation, nuclear localization, and the transcriptional activity of NF-κB, and TNF-α- or lipopolysaccharide-induced IL-6 secretion." (PMID 37759810, 2023). "Notably, levels of IL-6 and TNF-α were increased in lungs from 4T1.2-Luc2 tumor-bearing mice." (PMID 38033489, 2023).
tumor (continued). "In addition, the conversion of dietary tryptophan to indole by Lactobacillus prevented the reduction of tumour‐associated macrophage (TAM) aryl hydrocarbon receptor (AhR) activity and aggregation of intratumoural TNF‐α+ IFN‐γ+ CD8+ T cells, attenuating the efficacy of immunotherapy." (PMID 38082435, 2023). "Studies have shown that when there is a high concentration of TNF-α in tumors, TNF-α may selectively destroy blood vessels in tumor tissues and promote T cell immune response, but low concentrations of TNF-α may promote tumor progression and lead to poor prognosis." (PMID 36865498, 2023). "NSAIDs in vivo could also reduce tumor growth via TNF-α-mediated and TRAIL-induced apoptosis." (PMID 36765695, 2023). "Paclitaxel inhibits regulatory cells (Tregs) and tumor-associated macrophages (TAMs), stimulates anti-tumor immunity and leads to the release of pro-apoptotic molecules such as Fas L, TNF-related apoptosis-inducing ligand (TRAIL) and cytokines such as TNF-α and IFN-γ." (PMID 38005238, 2023). "Furthermore, TNFα may directly promote Treg activation through the TNF receptor type 2 (TNFR2) thereby suppressing anti-tumour immunity." (PMID 37455828, 2023). "However, more studies have found that TNF- α plays an important role in tumor progression." (PMID 37006260, 2023). "Tumor-growth factor (TGF) and platelet-derived growth factor (PDGF) induce the transformation of tumor fibroblasts (FHNR) in cancer-associated fibroblasts (CAFs), which play a key role in tumor progression, producing pro-tumoral cytokines (e.g., IL-6, IL-8, TNF, IL-10)." (PMID 37842234, 2023). "In tumor cells, TNF-α may induce apoptosis due to TNF receptor 1 signaling." (PMID 38069260, 2023). "Notably, single stimulation of either LMP1 or TNFα could only enhance the number of ordinary dot‐like invadopodia, suggesting that the EBV infection sensitizes the NPC cells to form mobilizing invadopodia when encountering a TNFα‐rich tumor microenvironment." (PMID 36420735, 2023). "However, TNF can also be a cancer killer, and its anti-tumor role may involve immune responses, e.g., promoting tumor stromal destruction by CTL or tumor-infiltrating macrophages." (PMID 37987366, 2023). "As anticipated, TNFα increased SF-767 cell invasion because of other metabolic stimuli due to the presence of LDL protein and receptors, which increased the cell proliferation turnover of growing tumor cells in this study and caused NF-κB p65 (RelA) activation." (PMID 37892820, 2023). "Thus, most of the upregulated miRNAs during T. denticola infection may be involved in tumor progression and metastasis by mediating the NFκB pathway, TNF signaling, or Wnt signaling pathways." (PMID 37569480, 2023). "Similarly, TNF-α possesses tumor-promoting capabilities by inducing hemorrhagic necrosis." (PMID 38137547, 2023). "Finally, NRPP inhibited tumour growth and downregulated the levels of TNF‐α, IL‐1β and IL‐6." (PMID 37610095, 2023). "Because TNF-α plays an important role in carcinogenesis and tumor progression, further studies on how M. hyorhinis-infected PCa cells induce expression and secretion of TNF-α may help elucidate the possible molecular mechanisms by which M. hyorhinis plays a role in PCa carcinogenesis." (PMID 37867861, 2023). "At the sites of initial tissue damage, infection or tumor formation, the attraction of pro-inflammatory T helper cells Th1 and Th17 and Natural Killer (NK) cells establishes the earliest defense against these insults by secreting IFNγ, IL-1β, TNF and related cytokines." (PMID 37296860, 2023). "With the progression of HCC, the tumor killing activity of NK cells decreases, with the characteristics of reduced expression of the NK cytotoxic factors granzyme and perforin, as well as reduced secretion of the tumor killing-related cytokines TNF-α and IFN-γ." (PMID 37275909, 2023).